KRAS (KRas proto-oncogene, GTPase)
Diseases named in the same sentence as KRAS in open-access papers (continued):
Sharing a sentence is not in itself a finding about the gene and the disease.
cancer (continued). "RAS genes (HRAS, KRAS, and NRAS) are the most frequently mutated gene family in cancer." (PMID 31681587, 2019). "Therefore, targeting oncogene addiction can be a viable strategy for treating refractory cancers driven by important oncogenes, such as KRAS, which are otherwise difficult to be targeted by small molecules." (PMID 30674639, 2019). "However, even in KRAS wild‐type patients, a germline variant in the let‐7 miRNA binding site of the KRAS 3′ UTR (rs61764370, KRAS‐variant) has been shown to increase risk for certain types of cancers and to predict treatment outcomes." (PMID 30536617, 2019). "The mechanism of the inhibition of cancer cells was evaluated by using the hypothesis of interpretation of KRAS oncogene expression." (PMID 31330954, 2019). "Further study into the functional link between KRAS and stromal PR-mediated signaling in these cancers is encouraged, as this may unveil important clues to their pathogenesis and open up for the discovery of novel treatment options." (PMID 31827798, 2019). "This last finding was confirmed by a different group which reported a prevalence of KEAP1-NFE2L2 (31%) alterations in tumors with high neuroendocrine gene expression, mainly co-occurring with STK11 and KRAS genes to exert a synergic role of tumorigenesis enhancement and cancer progression." (PMID 31126053, 2019). "Although KRAS could serve as an excellent drug target for many cancers, direct inhibition of oncogenic RAS has proven to be challenging." (PMID 31332011, 2019). "Therefore, accurate and ultrasensitive detection of KRAS mutations will provide a robust evidence for early diagnosis of mutant KRAS-related cancer." (PMID 30976068, 2019). "Since KRAS mutation accounts for more than 20% of all NSCLC and RAS is overexpressed in NSCLC patient tissues, we investigated the effect of KYA1797K, a small molecule which had an anti-cancer effect in CRC via degrading both β-catenin and Ras14, in KRAS mutated NSCLC." (PMID 30679620, 2019). "In line with this, clinical trials confirmed that patients with KRAS-mutant cancers generally have a poor response to the first generation of EGFR inhibitors, such as erlotinib and gefitinib, and the presence of KRAS mutations is used as a biomarker to exclude patients for EGFR inhibitor therapy." (PMID 31612108, 2019). "The frequency of two coexistent KRAS point mutations in cancer tissue did not associate with the histological type and was similar for ADC (4/16) and SCC (10/32) (p = 0.9)." (PMID 30368666, 2019). "However, the gradual activation of the other ERBB-family members functions as a compensatory mechanism that can reestablish KRAS signaling over time and make cancer cells TKI-resistant." (PMID 31266248, 2019). "Although KRAS, HRAS, and NRAS share functional similarities, KRAS missense gain-of-function mutations tend to occur on the 12th codon, while those in HRAS and NRAS occur on the 61st codon and are differentially utilized across cancer types." (PMID 31681559, 2019). "USP39 deubiquitinase is essential for KRAS proto-oncogene, GTPase (KRAS) oncogene-driven cancer." (PMID 30898977, 2019). "To determine the role of HFD in oncogenic KRAS-mediated aerobic glycolysis in cancer, we employed the KrasLSL-G12D/+;fElasCreERT mouse model that expresses mutant KrasG12D in one allele at an endogenous level in nearly 100% acinar cells upon tamoxifen induction (hereafter called KrasG12D/+)." (PMID 30819189, 2019). "Notably, KRAS expression was highly elevated in CAsE-PE cells, with pathway analysis supporting increased cell proliferation, cell motility, survival and cancer pathways." (PMID 31009485, 2019).
cancer (continued). "Thus, GLI inhibitors like GANT61 are advantageous in cancers where SMO contains an activating mutation or GLI activation is SHH ligand-independent and driven by e.g. KRAS mutations or by TGFβ-driven GLI2 expression." (PMID 31661013, 2019). "A notable example is KRAS, which is highly expressed in many types of cancer." (PMID 30975211, 2019). "Inhibiting KRAS function through regulating PM lipid PtdSer content may represent a viable strategy for KRAS-driven cancers." (PMID 31451509, 2019). "Collectively, aberrant lipogenesis and changes in lipid and glucose metabolism are key features of metabolic reprogramming, which may induce aberrant activation of KRAS signaling and a sustained pro-inflammatory environment, leading to cancer initiation." (PMID 30911103, 2019). "KRAS mutants are major drivers of cancers, such as colorectal, lung or pancreatic cancers." (PMID 31197133, 2019). "Compelling evidence showed that co-occurring genomic changes could profoundly affect biological behaviors, clinical outcomes, and therapeutic vulnerabilities of KRAS-mutant cancers." (PMID 31612108, 2019). "For example, USP39 has been shown to be essential for KRAS-driven cancer." (PMID 31332287, 2019). "For instance, gain‐of‐function mutations and overexpression of RAS family members (KRAS, HRAS, and NRAS) are among the most prevalent oncogenic lesions in human cancers, and high levels of Ras activity are necessary to maintain the transformed phenotype in some Ras‐driven cancers." (PMID 30422399, 2019). "Some cancer related pseudogenes could regulate the expression of their corresponding coding genes such as KRAS and KRASP1, KRAS, and KRASP1 by sequestering the interacting miRNAs." (PMID 31146489, 2019). "Importantly, the anti‐cancer activity of A17pro was verified in a human KRAS mutant LAC patient‐derived xenograft expressing high levels of pADAM17." (PMID 30833304, 2019). "Furthermore, KRAS mutant cancers depend on several proteasome components in genome scale RNAi screens." (PMID 30860482, 2019). "Besides, co-treatment of miR-139/LPN-HR and Afa/LPN-HR also significantly reduced the protein expression of Rac1 and KRAS and the associated phospho-Erk, phospho-MAPK, and COX-2, thereby notably weakening cancer cell growth and progression." (PMID 31426807, 2019). "Cancer-associated driver mutations in KRAS lock the protein into the GTP-bound state preventing the hydrolysis of GTP to GDP, resulting in constitutive signaling which give mutated cells a growth advantage and leads to development of cancer." (PMID 31399087, 2019). "The requirement for specific SNARE proteins for KRAS localization, signaling and gene regulation, suggests these SNAREs might play a role in KRAS-driven cancer." (PMID 31712554, 2019). "Similarly, human pancreatic mutant KRAS/CD133+ cancer cells derived from PDX models are sensitive to mitochondrial inhibition that leads these cells with stemness properties to apoptosis." (PMID 30413783, 2019). "Thus, strategies for targeting KRAS cancers have focused on downstream effectors, such as the MEK/ERK or PI3K/AKT pathways." (PMID 31296870, 2019). "Interestingly, the JAK1/2 inhibitor enhanced the growth inhibitory effect of the MEK-inhibitor, particularly in poorly immunogenic BRAF or KRAS mutant cancer cells (HT29 and SW620)." (PMID 30670049, 2019). "Among these kinases, KRAS is a clearly important component in the pathogenesis of cancer." (PMID 29896883, 2018).
cancer (continued). "As cooperation with oncogenic KRAS was observed in these cells, it is feasible that HNF1A provides additional oncogenic input, possibly by altering the differentiation state of KRAS-mutant, precancerous pancreatic cells or by expanding the resident stem cell/cancer stem cell population." (PMID 30074477, 2018). "By contrast, the cytosolic, inactive, fraction of NRF2 was not increased in KRAS mutated cancer cells." (PMID 29507676, 2018). "Other recent studies have attempted to define the genetic factors that may modify the cellular origin of KRAS-driven cancers." (PMID 30060526, 2018). "The overall mutational frequency of KRAS in cancer is 22% but with non-uniform distribution amongst different cancer types." (PMID 29851957, 2018). "Overall, PIK3CA mutations have been associated with KRAS mutant, MGMT methylated, and CIMP cancers; however, PIK3CA mutations in the catalytic exon 20 hotspot were found predominantly in BRAF mutant/MSI cancers." (PMID 30598662, 2018). "Developing drugs that target KRAS, the most frequently mutated oncogene in cancer, has not been successful despite much concerted efforts dedicated towards it in the last thirty years." (PMID 29534749, 2018). "Interestingly, a recent study identifies a new role for Gal-3 in which Gal-3 interaction with ανβ3 integrin drives cancer cell addiction to oncogenic KRAS." (PMID 29581864, 2018). "This discovery opens new avenues to target mutant KRas-dependent cancers." (PMID 30514931, 2018). "In contrast, the up-regulated genes were significantly implicated in several cancer hallmark-related activities, including epithelial-mesenchymal transition (EMT), interferon gamma response, up-regulation of the KRAS signaling pathway, hypoxia, and TNFA signaling mediated by NF-κB." (PMID 30240750, 2018). "This is especially true for KRAS, given its prominence in human cancers." (PMID 30194290, 2018). "Similarly, KRAS is expected to be closely related to anchorage-independent cancer cell growth in colorectal cancer cell lines." (PMID 30509235, 2018). "Moreover, KRAS-driven cancer cells can scavenge branch chain amino acids (i.e., isoleucine, valine, and leucine) and convert them into acetyl-CoA to fuel the TCA cycle." (PMID 28748451, 2018). "We observed that DMF is highly cytotoxic in primary and genetically modified cancer cells harbouring KRAS mutations, whilst it was rather cytoprotective in non-tumorigenic cells." (PMID 29507676, 2018). "As a control, we randomly selected 12 cancer type–matched cell lines without simultaneous mutations in KRAS and SMAD4 (hereafter referred to as Control cell lines) for which published in vitro radiosensitivity data were available." (PMID 30220971, 2018). "DASH could effectively enrich for a rare mutant variant of the KRAS gene in synthetic gDNA mixtures with a guide sequence against wild-type KRAS, mimicking the situation where rare cancer cells need to be detected in a pool of normal cells." (PMID 29514322, 2018). "The G12S and G12D mutations are located at the interface between KRAS and these partners, indicating that these SAPs may affect cell apoptosis-related functions via interrupting the connections between KRAS and its downstream elements, leading to cancer." (PMID 29662108, 2018). "Otherwise, oncogenic alterations in genes such as MYC and KRAS could reprogram glutamine metabolism in cancer cells." (PMID 30419950, 2018). "Two out of six mutations (PIK3CA H1047R and KRAS G12C) was associated with sensitivity in either the cancer-type-specific or the non-specific setting." (PMID 30053901, 2018).
cancer (continued). "Due to the decreased binding with BRAF, the activation of ERK, and the similar cancer transformation properties to KRAS G12V, we wanted to test whether RHEB Y35N transforms cells through the RAF/MEK/ERK pathway." (PMID 29320991, 2018). "Since KRAS promotes cell proliferation and inhibition of apoptosis and gal-3 appears to enhance KRAS activity through different mechanisms, it is conceivable that this interaction enhances cancer progression." (PMID 29463063, 2018). "Indeed, mutant KRas-dependent human cancer cells undergo apoptosis only when both GSK3α and GSK3β are knocked down simultaneously." (PMID 30514931, 2018). "These three cancer types have the highest occurrence of oncogenic KRAS." (PMID 29359686, 2018). "Metabolic reprogramming is as a hallmark of cancer, and several studies have reported that BRAF and KRAS tumors may be accompanied by a deregulation of cellular metabolism." (PMID 29907857, 2018). "Moreover, we assumed that in all simulations there were 35 KRAS-mutant cancer cells which are resistant to the monoclonal antibodies Panitumumab and Cetuximab." (PMID 35847834, 2018). "Firstly, CDK1 can be the SL partner gene of the cancer genes KRAS and MYC." (PMID 29855504, 2018). "Among these, oncogenic KRAS mutation signaling has been recently shown to play a predominant role in multiple aspects of PDAC metabolism, including adaptive metabolic responses and cancer cells-PSCs mutualism." (PMID 29458370, 2018). "Mitogen‐activated protein kinase has been considered as a druggable target for KRAS mutant cancer." (PMID 29896883, 2018). "This assay could be used to distinguish between a mutant type and wild‐type, and thus, three recurrent oncogenic point mutations in genes KRAS, PIK3CA and IDH1 in human cancer cell lines have been identified." (PMID 30338908, 2018). "Interestingly, we found the KRAS mutation spots in COAD are more dispersed compared with PAAD and LUAD, which are the other two cancer types with over 20% KRAS frequency." (PMID 30406144, 2018). "Two studies that examined large cohorts of stage II and III CRC reported that MSS cancers with a BRAF mutation had a worse prognosis compared to those with a KRAS mutation, and this was independent of disease stage and adjuvant treatment." (PMID 30598662, 2018). "Essentially, we showed that CD147 exhibits an identical surface expression pattern in a model of a KRas-transfected/transformed cell line (MCF10A-KRasG12V) as well as in pancreatic (KP3), lung (H2444), and colon (SW620) cancer cell lines expressing KRas mutants endogenously." (PMID 29899869, 2018). "To assess whether our filtering strategy retained known somatic mutations, we tested the impact of this strategy on the hotspot mutations in five known cancer-associated genes: BRAF, RAS family (HRAS, NRAS, and KRAS), and stop-gain NF1 gene mutations." (PMID 30662871, 2018). "A link between the cell cycle effects of NEK9 silencing and CDK4 suppression was suggested by pharmacological studies in which the CDK4 inhibitors palbociclib and ribociclib also induced a G1‐phase cell cycle arrest and senescence in the NRAS‐ and KRAS‐mutant cancer cell lines." (PMID 29112787, 2018).
cancer (continued). "Erastin could be also another potential drug to increase BRAFi therapy, due to the fact that it is an XC− inhibitor and this compound exhibits greater lethality in cancer cells harboring mutations in HRAS, KRAS, or BRAF30,31." (PMID 29487283, 2018). "In addition, the cue from the GradientScanSurv plot shows that higher expression of the KRAS gene is associated with faster death, which is expected from the known RAS biology in LUAD cancer study." (PMID 30517129, 2018). "Our studies identified NEK9 and CDK16 as two dabrafenib‐specific kinase targets and provide evidence that inhibition of NEK9 and CDK16 may underlie the greater effectiveness of this drug against NRAS‐ and KRAS‐mutant cancer cells." (PMID 29112787, 2018). "Moreover, in KRAS-driven cancer including PDACs, miR-200 expression was suppressed by KRAS activation." (PMID 30542509, 2018). "In summary, PIP5K1A loss reduces oncogenic KRAS signaling, which could potentially be capitalized upon to add specificity to MAPK inhibitors for the treatment of KRAS-mutant cancers like PDAC." (PMID 30194290, 2018). "Understanding the specific genomic vulnerabilities of KRAS-driven cancers may uncover novel patient-tailored treatment options." (PMID 30482246, 2018). "Furthermore, KRAS-driven glutamine (Gln) metabolism becomes a major source of carbon and nitrogen for cancer cells proliferation." (PMID 29458370, 2018). "The first KRAS renaissance, after the original description of mutant KRAS forms as a protooncogene, is manifested in the observation that mutant KRAS is found in approximately 30% of all human cancers." (PMID 30283732, 2018). "Overall, the present pipeline may be employed as a robust technology in: i) drug and diagnostic target discovery, ii) therapeutic monitoring in the context of cancer immunotherapy, and iii) biology of KRas-driven cancers." (PMID 29899869, 2018). "Although the tumors lacking mutations in EGFR and KRAS showed a higher mutational/candidate neoantigen level than KRAS-mutant carcinomas, this difference was not statistically significant." (PMID 30097571, 2018). "In addition, the PNA probe design can be modified in the detection of other somatic mutations, such as EGFR, KRAS, or BRAF mutations in many cancers." (PMID 29104223, 2017). "Notably, Poloppin and Poloppin-II sensitize mutant KRAS-expressing cancer cells to inhibition of the tyrosine kinase receptor c-MET." (PMID 28807782, 2017). "Thus, our findings suggest that PLK1 and PLK4 inhibition underlies the activity of Poloppin in triggering mitotic arrest, and in preferentially killing cancer cells that express mutant oncogenic KRAS." (PMID 28807782, 2017). "The prognostic value of KRAS expression has been determined in various cancers." (PMID 29029494, 2017). "Human cancer genomics data also provides evidence of the oncogenicity of G12R and G13R substitutions in RAS proteins: KRASG12R accounts for >10% of KRAS-driven PDACs, while HRASG13R is the fourth most frequent HRAS mutation in human cancers and NRASG13R is common in colorectal cancers." (PMID 29233960, 2017). "In particular, SW48 and LIM1215 cancer cells, that are wild type (WT) for KRAS, BRAF, NRAS and PIK3CA genes, and GEO cancer cells, that have a KRAS codon 12 mutation, are sensitive to the anti-epidermal growth factor receptor (EGFR) monoclonal antibody cetuximab." (PMID 28978118, 2017). "Furthermore, recent studies have shown that LCC benefits more from cetuximab treatment than RC among KRAS wild‐type cancers." (PMID 28948714, 2017).